IGFBP2 (insulin like growth factor binding protein 2)
Diseases named in the same sentence as IGFBP2 in open-access papers (continued):
Sharing a sentence is not in itself a finding about the gene and the disease.
lung disease (3 papers, 2022 to 2025). "The RNA-seq analyses revealed that IGFBP2 was significantly downregulated in AEC2 cells from the COVID-ARDS group compared with those from other lung disease groups combined (IPF alone and IPF with COVID history)." (PMID 40121473, 2025). "Using multicolor immunohistochemistry, we demonstrated that protein expression levels of IGFBP2 as well as its selective ligands IGF1 and IGF2 were significantly downregulated in AEC2 cells of the lung disease groups compared with healthy controls." (PMID 40121473, 2025). "Based on pathway enrichment analysis, genes altered in BPD blood cells were mainly enriched in cell cycle regulation and arrest (e.g., PPP2CA, RBL2, CENPU, CCNY, CDK6) and pulmonary disorder and developmental disorders (e.g., AGER, ITGA6, CA4, BACH2, IGFBP2, BMPR2, SKI, DAB2)." (PMID 35484630, 2022).
meningioma (3 papers, 2017 to 2023). A generally slow growing tumor attached to the dura mater. "We believed that IGFBP2 and METTL3 were survival-related m6A regulatory genes with critical prognostic value in meningiomas." (PMID 37910780, 2023).
metastatic tumor (3 papers, 2011 to 2021). "They carried out a cDNA microarray analysis on both the primary and metastatic tumor (cervical lymph node) and found that IGFBP2 (insulin-like growth factor binding protein-2) was overexpressed in both tumor specimens." (PMID 24212625, 2011). "The clinical implications of the current study and future ones might include a new stratification of RMS patients with metastatic disease according to the levels of secreted IGFBP2 and anti-IGFBP2 antibodies and a further characterization of liquid biopsies in pediatric cancer patients." (PMID 32093404, 2020).
myocardial infarction (3 papers, 2022 to 2023). Gross necrosis of the myocardium, as a result of interruption of the blood supply to the area, as in coronary thrombosis. "Among patients who suffered acute myocardial infarction, plasma levels of IGF-1 and IGFBP-2 were lower and higher, respectively, as compared to healthy controls (both p < 0.05)." (PMID 36970368, 2023).
osteosarcoma (3 papers, 2017 to 2023). A usually aggressive malignant bone-forming mesenchymal neoplasm, predominantly affecting adolescents and young adults. "Specifically, the association of circulating IGFBP2 concentrations and primary osteosarcoma gene expression profiles based upon 46 patients with osteosarcoma were explored." (PMID 28732082, 2017). "A novel but poorly annotated and non-sex linked gene, called C4orf3, was identified to have reduced expressions in primary osteosarcoma tumors where circulating IGFBP2 concentrations were categorized as high." (PMID 28732082, 2017). "As such, whether circulating IGFBP2 cannot be used as a direct biomarker of osteosarcoma burden requires additional investigation." (PMID 28732082, 2017). "Given the known chaotic genomic landscape of osteosarcoma, perturbations in multiple signaling pathways are likely in sarcomagenesis, and the finding that IGFBP2 alone does not drive hierarchal clustering is not an unexpected scientific outcome." (PMID 28732082, 2017). "Finally, IGFBP2 expression was decreased in groups not treated with exogenous AGEs, which has been found in rat osteosarcoma cells." (PMID 36835011, 2023).
osteosclerosis (3 papers, 2010 to 2025). Abnormally high bone density. "This anabolic effect is consistent with the recent finding that IGF2 and IGFBP2 levels and bone formation are increased in patients with osteosclerosis linked to hepatitis C." (PMID 20573191, 2010).
pancreatic diseases (3 papers, 2016 to 2023). "The IGF-1/IGFBP-2 ratio turned out to be a good marker of pancreatic diseases, but insufficient for the purpose of CP and PDAC differentiation." (PMID 37373743, 2023). "On the other hand, the markers other than IGFBP2 exhibited significant AUC values discriminating most pancreatic diseases from IDACP." (PMID 27579675, 2016). "However, our present results confirm that the IGF-1/IGFBP-2 ratio can only differentiate general pancreatic diseases from the group of healthy patients." (PMID 37373743, 2023). "Among these proteins, six (AAT, IGFBP2, RAB2B, PRDX2, RHOC, and LMNA) with functions closely related to pancreatic disease were selected for further validation." (PMID 36712921, 2023). "IGFBP2, 3, CA19-9 and DUPAN-2 as markers in patients with pancreatic diseases other than IDACP." (PMID 27579675, 2016).
pancreatitis (3 papers, 2017 to 2023). Inflammation of the pancreas. "In our cohort, the IGFBP-2 levels were comparable among patients with liver cirrhosis, cholangitis, and pancreatitis." (PMID 38137505, 2023). "The higher level of TIMP1, the lower the level of APOA4, APOC3 and IGFBP2 in PC, compared with healthy controls or patients with pancreatitis." (PMID 28514751, 2017). "Four proteins (APOA4, APOC3, IGFBP2 and TIMP1) were significantly altered in PC compared with healthy subjects or pancreatitis using Kruskal-Wallis test (P < 0.01)." (PMID 28514751, 2017).
Pleural effusion (3 papers, 2018 to 2025). The presence of an excessive amount of fluid in the pleural cavity. "We also identified pleural effusion predictive gene signatures, including TMPRSS3, MS4A7, NAPSA, and IGFBP2, while liver metastasis predictive markers included WFDC2, HSPB1, COX6C, APOE, and TUBA1A." (PMID 39955556, 2025).
post-traumatic stress disorder (3 papers, 2019 to 2025). An anxiety disorder precipitated by an experience of intense fear or horror while exposed to a traumatic (especially life-threatening) event. "IGFBP-2 has shown an influence on behavior and raised potential as a therapeutic treatment method for patients with post-traumatic stress disorder (PTSD), both acute and chronic." (PMID 37834128, 2023). "In adult male rats, IGFBP-2 (1 μg/kg, i.v.)increased the density of mature dendritic spines and total spine density in the DG and medial prefrontal cortex, which is the underlying mechanisms explaining the therapeutic-like effects of IGFBP-2 in post-traumatic stress disorder (PTSD)." (PMID 31824433, 2019).
preeclampsia (3 papers, 2018 to 2025). Preeclampsia is a hypertensive disorder of pregnancy that is characterized by new-onset hypertension with proteinuria presenting after 20 weeks of gestation, and depending on mild or severe forms may initially present with severe headache, visual disturbances, and hyperreflexia. "Therefore, this study employed human tissue samples and in vitro cultured trophoblast cells to investigate the association between IGFBP2 and the pathogenesis of preeclampsia." (PMID 40728947, 2025). "Researchers aim to investigate the clinical significance and elucidate the molecular mechanisms of IGFBP2 in the pathogenesis of preeclampsia." (PMID 40728947, 2025). "Similarly, the findings indicated that IGFBP2 is reduced in the placental tissues derived from preeclampsia placental tissue related to EMT inhibition." (PMID 40728947, 2025). "The findings of this study indicate that IGFBP2 may play a critical role in the pathogenesis of preeclampsia, thereby offering a novel avenue for further investigation into the underlying mechanisms of this condition." (PMID 40728947, 2025). "Future studies could further investigate expression profiles of IGFBP2 during early pregnancy and evaluate the potential utility of measuring IGFBP2 levels in early gestation for predicting preeclampsia." (PMID 40728947, 2025). "This study identified that the IGFBP2 expression downregulation and EMT process was inhibited in the placental tissue of PE patients, suggesting that IGFBP2 and EMT play an important role in the development of preeclampsia." (PMID 40728947, 2025). "In summary, the activation of the IGFBP2-mediated PI3K/AKT signaling pathway enhances the proliferation, migration, invasion, and EMT of trophoblast cells in preeclampsia." (PMID 40728947, 2025).
psoriasis (3 papers, 2017 to 2022). An autoimmune condition characterized by red, well-delineated plaques with silvery scales that are usually on the extensor surfaces and scalp. "In contrast, healthy keratinocytes undergoing senescence were characterized by low p21 and IGFBP2 levels, and resulted to be more susceptible to the pro-apoptotic action of psoriasis-related inflammatory cytokines." (PMID 32302288, 2020). "This suggests a potential involvement of IGFBP2 in cell cycle arrest and senescence of keratinocytes of psoriasis lesions." (PMID 32302288, 2020). "To date, the expression, regulation and function of IGFBP2 in psoriasis remain unexplored." (PMID 32302288, 2020). "We further investigated the expression and regulation of IGFBP2, p16 and p21 in keratinocytes isolated from NLS areas, left untreated or treated with combinations of psoriasis-related pro-inflammatory cytokines." (PMID 32302288, 2020).
renal dysfunction (3 papers, 2020 to 2023). "Elevated plasma IGFBP-2 levels in patients with septic shock may indicate either disease severity or renal dysfunction." (PMID 38137505, 2023). "However, our results showed that the level of IGFBP-2 was not correlated with clinical parameters of renal dysfunction (p > 0.05)." (PMID 33134397, 2020).
sarcopenia (3 papers, 2022 to 2024). Progressive decline in muscle mass due to aging which results in decreased functional capacity of muscles. "It is unrigorous to conclude a definitive association between IGFBP2 and sarcopenia based on a limited sample size and a single set of results." (PMID 39725826, 2024). "In the proteomic analysis, IGFBP2 was found to be significantly up-regulated in individuals with sarcopenia." (PMID 39725826, 2024). "Our study investigated the plasma proteome of individuals with age-related sarcopenia and identified 8 DEPs that showed promising predictive performance, including IGFBP2, PON3, LRG1, PRDX6, PTGDS, CD163, PRG4, and TRAJ17." (PMID 39725826, 2024). "Thus, we speculate that IGFBP2 might undergo various modifications during sarcopenia pathogenesis, which may alter the targeted antigenic epitope for recognition and affect the affinity of antigen binding, ultimately resulting in detection discrepancies." (PMID 39725826, 2024). "Protein modifications of IGFBP2 might exhibit during sarcopenia pathogenesis." (PMID 39725826, 2024). "Subsequent ELISA validation in an independent cohort confirmed significantly different expression levels of PON3 and IGFBP2 between individuals with and without sarcopenia." (PMID 39725826, 2024). "In the cohort for proteomic analysis, compared with those without sarcopenia, individuals with sarcopenia exhibited older age, higher inflammatory levels, higher aCCI, and higher number of drugs, which could influence IGFBP2 expression level." (PMID 39725826, 2024). "IGFBP2 (AUC 0.8756) and PON3 (AUC 0.8344) demonstrated the top 2 AUC values, indicating their decent ability to differentiate individuals with sarcopenia from those without sarcopenia." (PMID 39725826, 2024).
type 1 diabetes (3 papers, 2012 to 2024). "Poor glycaemic control in type 1 diabetes was associated with increased IGFBP2 proteolysis in albuminuric subjects." (PMID 23781310, 2012). "In contrast to the ND individuals, in longitudinal serum and plasma proteomics studies, lower and decreasing levels of IGFBP2 were reported prior to the clinical manifestation of type 1 diabetes." (PMID 37537394, 2023). "In human studies, IGFBP2 has been reported to correlate inversely with insulin levels, and in the cross-sectional serum proteomics study by Zhi and co-workers, elevated IGFBP2 was observed and validated in individuals with type 1 diabetes." (PMID 37537394, 2023).
adrenocortical tumor (2 papers, 2012 to 2013). "In support of the hypothesis of a tumor-growth-promoting effect of IGFBP-2 is the observation that Y-1 mouse adrenocortical tumor cells overexpressing IGFBP-2 show increased tumorigenic potential and cell proliferation." (PMID 22927847, 2012).
amyotrophic lateral sclerosis (2 papers, 2019). Amyotrophic lateral sclerosis (ALS) is a neurodegenerative disease characterized by progressive muscular paralysis reflecting degeneration of motor neurons in the primary motor cortex, corticospinal tracts, brainstem and spinal cord. "The number of IGFBP-2-positive cells was decreased in the hippocampus of a mouse model of amyotrophic lateral sclerosis (ALS)." (PMID 31824433, 2019).
aneurysm (2 papers, 2019 to 2024). Bulging or ballooning in an area of an artery secondary to arterial wall weakening. "Despite the bulk of associative evidence, how IGFBP2 mechanistically causes or prevents thoracic and abdominal aneurysm formation will require future studies to elucidate." (PMID 39590192, 2024). "We selected and validated the genes randomly (Lrrc17, Gxylt2, Mfsd2a, Scube and Ank2) and based on their role in aneurysms (Mmp12, Spp1, Ctss) or cardiovascular complications (Mfap4, Igfbp2) or inflammatory signalling pathways (Ccls and Ccrs)." (PMID 30677223, 2019).
asthma (2 papers, 2022 to 2025). "The proteins that are regulated by LPS and were previously shown to be implicated in asthma and in ASM proliferation also include the upregulation of matrix-metalloproteinase-1 (MMP-1) and Abelson interactor 1 (Abi1) and the downregulation of insulin-like growth factor-binding protein 2 (IGFBP-2)." (PMID 36359743, 2022).
autoimmune disease (2 papers, 2018 to 2021). A disorder resulting from loss of function or tissue destruction of an organ or multiple organs, arising from humoral or cellular immune responses of the individual to their own tissue constituents. "In various autoimmune diseases, IGFBP2 can be as potential biomarker and therapeutic target." (PMID 34527446, 2021). "In addition, some IGFBPs such as IGFBP2 were proved to be increased in several different autoimmune diseases including T1DM, MS, RA, SLE, and IBD." (PMID 30214426, 2018). "It is not clear whether IGFBP2 is a general marker for autoimmunity or it is specific to certain kind of autoimmune diseases." (PMID 30214426, 2018).
Barrett esophagus (2 papers, 2015 to 2019). Esophageal lesion lined with columnar metaplastic epithelium which is flat or villiform. "IGFBP2 expression levels in a progression series of human esophageal tissues including Barrett's metaplasia, low-grade dysplasia, high-grade dysplasia and EAC were examined by Affymetrix HG-U133A oligonucleotide microarray." (PMID 26317790, 2015).
basal cell carcinoma (2 papers, 2014 to 2023). A carcinoma involving the basal cells. "The up-regulation of IGFBP2 was reported in both murine and human basal cell carcinoma (BCC), which promoted BCC development by mediating epidermal progenitor cell expansion via Hedgehog (Hh) signaling pathway." (PMID 38099574, 2023). "Evidence has strongly suggested an association between Shh and the insulin like growth factor binding protein-2 (IGFBP-2) in the transformation of normal HF to basal cell carcinoma." (PMID 24451143, 2014).
bipolar disorder (2 papers, 2011 to 2020). A disorder of the brain that causes unusual shifts in mood, energy, activity levels and the ability to carry out day-to-day tasks. "It was observed that IGF Binding Protein-2 (IGFBP-2) level decreased in the brain in bipolar disorder." (PMID 32283906, 2020).
Cachexia (2 papers, 2019 to 2023). Severe weight loss, wasting of muscle, loss of appetite, and general debility related to a chronic disease. "Igf1 modifiers that are co‐regulated during toxin‐induced weight loss (Igfbp1, Igfbp2, and Igfals) are also worthy of consideration as druggable targets in cachexia." (PMID 30782979, 2019).
cardiac hypertrophy (2 papers, 2023 to 2025). "Gdf15 is recognized as a SASP factor within the cardiovascular system, where its accumulation has been associated with the development of cardiac hypertrophy while Igfbp2 is another SASP protein associated with aging." (PMID 40607964, 2025). "Given the role of the PTEN/AKT/mTOR pathway in cardiac hypertrophy and fibrosis, IGFBP2’s modulatory effect on PTEN may influence AF development." (PMID 37435047, 2023).
chordoma (2 papers, 2014 to 2016). Chordomas are rare malignant tumors arising from embryonic remnants of the notochord in axial skeleton. "IGF-binding protein-2 (IGFBP-2) was among the genes found to be upregulated in chordoma compared with benign intervertebral disk." (PMID 27200287, 2016). "We demonstrate the expression of new potential candidates for chordoma tumorigenesis, such as CD24, ECRG4, RARRES2, IGFBP2, RAP1, HAI2, RAB38, osteopontin, GalNAc-T3, VAMP8 and others." (PMID 24452533, 2014).
chorioamnionitis (2 papers, 2021 to 2023). A morphologic finding indicating inflammation of the fetal sac membranes. "In contrast, our group previously reported that low plasma levels of IGFBP-2 were independently associated with histologic chorioamnionitis in women with preterm labor." (PMID 33857242, 2021).
Down syndrome (2 papers, 2023 to 2024). "A study analysing astrocyte protein secretion and gene expression in three mouse models of genetic neurodegenerative diseases (Rett, Fragile X and Down syndrome) showed that astrocytes secrete the IGF2 inhibitory protein IGFBP2, causing learning and memory failure." (PMID 37108327, 2023).
glaucoma (2 papers, 2015 to 2022). Increased pressure in the eyeball due to obstruction of the outflow of aqueous humor. "Expression of proteins enriched in the vitreous (CCL2, IGFBP2, MMP10, HGF, TNFRSF11B (OPG)) was localized by immunohistochemistry in eyes of patients with severe ischemic CRVO followed by secondary glaucoma." (PMID 25978399, 2015).
Glucose intolerance (2 papers, 2016 to 2020). Glucose intolerance (GI) can be defined as dysglycemia that comprises both prediabetes and diabetes. "Obese humans with glucose intolerance have increased DNA methylation at IGFBP2 in peripheral blood cells, and the IGFBP2 locus is hypermethylated in association with decreased expression in liver biopsy specimens from individuals with NASH." (PMID 31389294, 2020).
head and neck cancer (2 papers, 2010 to 2021). A primary or metastatic malignant neoplasm affecting the head and neck. "This study aimed to investigate the potential of fermented CJ dried fruit extracts as a new source of cancer treatment, the role of IGFBP-2 overexpression in the development of head and neck cancer, and their mechanisms." (PMID 34728751, 2021). "One other study showed elevated levels of IGFBP1 (and IGFBP2) in plasma of patients with head and neck cancers." (PMID 20559444, 2010). "However, the role of IGFBP-2 in head and neck cancer remains unclear." (PMID 34728751, 2021).
hemolytic-uremic syndrome (2 papers, 2021 to 2023). Acute kidney injury associated with microangiopathic hemolytic anemia and thrombocytopenia. "This study aimed to investigate the clinical significance of serum IGFBP2 as a biomarker for disease activity and severity in hemolytic uremic syndrome (HUS) induced by enterohemorrhagic Escherichia coli (EHEC)." (PMID 33641616, 2021). "Furthermore, the serum levels of IGFBP-2 correlated positively with markers indicating the disease severity of patients with hemolytic uremic syndrome." (PMID 38137505, 2023). "Hemolytic uremic syndrome, a serious complication arising from infection with enterohemorrhagic Escherichia coli, found that patients with severe cases displayed higher serum levels of IGFBP-2 than healthy controls." (PMID 38137505, 2023).
Hepatic fibrosis (2 papers, 2024 to 2025). The presence of excessive fibrous connective tissue in the liver. "Interestingly, we did not observe a significant correlation between the serum level of IGFBP2 and the hepatic fibrosis indicator LSM in patients with MASLD in this research." (PMID 40608848, 2025). "Thus, we also evaluated the association between the serum level of IGFBP2 and the LSM value (a hepatic fibrosis predictor from FibroScan)." (PMID 40608848, 2025).